TREML4 (triggering receptor expressed on myeloid cells like 4)
Description:
Positively regulates Toll-like receptor TLR7 signaling in macrophages.
Synonyms: TLT-4; TLT4
Tractability: Antibody: UniProt places it where antibodies can reach, with high confidence; its Gene Ontology location is reachable by antibodies, with high confidence; UniProt predicts a signal peptide or a membrane-spanning region; the Human Protein Atlas places it where antibodies can reach.
Gene: Protein-coding gene on chromosome 6 (41,228,339 to 41,238,882, forward strand). Ensembl gene ENSG00000188056.
Subcellular location: Secreted
Subcellular location (Human Protein Atlas): Plasma membrane; Predicted to be secreted
Pathways (Reactome):
Immune System: Immunoregulatory interactions between a Lymphoid and a non-Lymphoid cell
Gene Ontology:
Molecular function: signaling receptor activity
Biological process: positive regulation of toll-like receptor 7 signaling pathway
Cellular component: cell surface; plasma membrane; extracellular region
Genetic constraint (gnomAD): Loss-of-function variants: 25 observed, 26.39 expected, observed/expected ratio (o/e) 0.95, 90% interval 0.69 to 1.32. The upper end of that interval is the gene's LOEUF score, 1.32, which puts it in group 5 of 6, group 1 being the genes least tolerant of losing a copy. Missense variants: 268 observed, 245.06 expected, observed/expected ratio (o/e) 1.09, 90% interval 0.99 to 1.21. Synonymous variants: 92 observed, 90.75 expected, observed/expected ratio (o/e) 1.01, 90% interval 0.86 to 1.21.
Homologues: Orthologues: chimpanzee TREML4 (98% identical), mouse Treml4 (54% identical), rat Treml4 (53% identical), tropical clawed frog trem2 (18% identical). Paralogues in human: NCR2 (38% identical), TREML2 (24% identical).
Diseases named in the same sentence as TREML4 in open-access papers:
TREML4 is named in the same sentence as 23 diseases in open-access papers, as found by Europe PMC text mining. Sharing a sentence is not in itself a finding about the gene and the disease. The quoted sentences say what the papers report.
atherosclerosis (6 papers, 2019 to 2023). A disease characterized by the build-up of fatty material and calcium deposition in the arterial wall resulting in partial or complete occlusion of the arterial lumen. "In conclusion, this study evaluated the relationship between gene expression and TREML4 polymorphisms in patients with subclinical atherosclerosis compared to a control group and LV dysfunction after MI." (PMID 36329152, 2022). "TREML4 and other members of the triggering receptor expressed in the myeloid cell family are associated with a risk of atherosclerosis and progression in coronary artery disease, acute coronary syndrome, and coronary artery calcification." (PMID 36329152, 2022). "Herein, the relationship between TREML4 expression and its polymorphisms (rs2803495 and rs280396) was evaluated in patients with subclinical atherosclerosis (n = 340) and heart failure post-acute myocardial infarction (MI) (n = 68) for the first time." (PMID 36329152, 2022). "In this study, they also showed that combined apoE and TREML4-deficient mice developed less atherosclerosis with reduced macrophage and monocyte content as well as decreased collagen deposition, compared with apoE-deficient control mice." (PMID 34572399, 2021). "Here, we study the role of Treml4 in pro-inflammatory macrophages and atherosclerosis progression; both key underlying aspects of most cardiovascular diseases." (PMID 32292401, 2020). "TREML4 also has an important association with the extent of coronary lesion, but few studies have evaluated its relationship with the process of atherosclerosis." (PMID 31076644, 2019). "TREML4 was upregulated in HD in both CD14 clusters and expression on monocytes has been associated with inflammation and increased risk for atherosclerosis." (PMID 37361874, 2023). "In a murine model of atherosclerosis, we found that Treml4 favors development of disease by exacerbating lesion burden, macrophage content, stage scores, and vulnerability features of advanced atherosclerotic lesions." (PMID 32292401, 2020). "Because calcification is only one characteristic of late atherosclerosis, we next investigated if Treml4 influenced plaque composition, a key consideration for disease outcome." (PMID 32292401, 2020). "Transcriptome analysis confirmed that murine Treml4 controls the expression of genes related to inflammation and lipid regulation pathways, suggesting a possible role in atherosclerosis." (PMID 32292401, 2020). "Consistent with the lower foam cell and macrophage positive area, we found that Apoe–/–/Treml4–/– mice had lower levels of circulating Ccl2 while other cytokines relevant to atherosclerosis remained unchanged." (PMID 32292401, 2020). "Our transcriptional profiling of BMDM upon oxLDL loading provides important insight to our understanding of the role of Treml4 in macrophages and in the murine model of atherosclerosis." (PMID 32292401, 2020). "Further research is needed to decipher the role of TREML4 in human atherosclerosis." (PMID 34572399, 2021). "This, together with our previous demonstation of association between TREML4 polymorphisms and cardiovascular calcification led us to ask whether Treml4 might contribute to atherosclerosis progression." (PMID 32292401, 2020). "To investigate whether atherosclerosis progression was affected by Treml4 expression, we assessed early, intermediate, and advanced disease stages in Apoe–/–/Treml4–/– knockout mice and Apoe–/– controls after feeding a WD for 2, 8, and, 16 weeks." (PMID 32292401, 2020). "In conclusion, TREML4 mRNA expression in blood leukocytes is influenced by minor alleles (G and C) and may regulate differently during the atherosclerosis progression stages, but not in asymptomatic atherosclerosis disease and post-MI." (PMID 36329152, 2022). "In addition, TREML4 is highly expressed in patients with atherosclerosis." (PMID 34572399, 2021).
atherosclerosis (continued). "Therefore, TREML4 expression is a potential marker of atherosclerosis severity and may be useful for monitoring patients with CAD." (PMID 31076644, 2019). "Since macrophage activation during the development of atherosclerosis is driven by LDL particles, particularly oxidized LDL (oxLDL), we tested the ability of oxLDL to induce Treml4 expression in murine BMDM." (PMID 32292401, 2020). "Here we report for the first time that Treml4 affects inflammatory programs in macrophages as well as plaque composition during the development of atherosclerosis, although it does not appear to directly affect plaque calcification in our murine model." (PMID 32292401, 2020).
acute coronary syndrome (3 papers, 2019 to 2022). Signs and symptoms related to acute ischemia of the myocardium secondary to coronary artery disease. "TREML4 is upregulated in the early phase of acute coronary syndrome." (PMID 31076644, 2019).
coronary artery calcification (3 papers, 2019 to 2022). Calcification of the coronary artery, used as a measure of coronary atherosclerosis, a risk factor for myocardial infarction. "We have previously found that TREML4 expression positively correlates with human coronary arterial calcification (CAC)." (PMID 32292401, 2020).
coronary artery disease (3 papers, 2019 to 2022). "In a previous study, we analyzed the expression of TREML4 and its polymorphisms in blood leukocytes from 137 patients with coronary artery disease." (PMID 36329152, 2022). "We previously investigated the relationship between gene expression and TREML4 polymorphisms in patients with coronary artery disease undergoing coronary angiography." (PMID 36329152, 2022). "We investigated the relationship between the mRNA expression of 13 genes in blood leukocytes, TREML4 polymorphisms, and coronary artery lesion extension (Friesinger index) in patients with coronary artery disease (CAD) (n = 137)." (PMID 31076644, 2019). "Other groups have also identified dysregulated TREML4 expression in patients with acute coronary syndrome, Alzheimer’s disease, post-stenotic collateral coronary artery disease and coronary artery disease." (PMID 32292401, 2020).
diabetes mellitus (2 papers, 2019 to 2022). A metabolic disorder characterized by abnormally high blood sugar levels due to diminished production of insulin or insulin resistance/desensitization. "Diabetes mellitus was more frequent among patients who expressed TREML4 mRNA above the median (p = 0.015), and these subjects more frequently used antidiabetics (p = 0.001)." (PMID 31076644, 2019). "A high frequency of diabetes mellitus (OR 3.7, CI 1.1–11.8, p = 0.029) as well as antidiabetic use (OR 13.0, CI 2.2–33.9, p = 0.002) were observed in patients who had high TREML4 mRNA levels, and these patients also presented more extensive atherosclerotic lesions." (PMID 31076644, 2019).
lupus (2 papers, 2020). "The higher frequency of the T allele in our African American lupus patients, which correlates with increased TREML4 expression, suggests a potential for a more robust response to TLR stimulation." (PMID 33108347, 2020). "Mouse studies suggest that Treml4 potentiates Toll-like receptor 7 (Tlr7) signaling in a model of systemic lupus erythematosus and genetic Treml4 deficiency protects animals from lupus-associated kidney failure, increased levels of inflammatory cytokines, and autoantibodies." (PMID 32292401, 2020). "TREML4 expression has been described specifically in splenic macrophages and Ly6Clo monocytes and plays a role in lupus, an autoimmune disease characterized by inflammation in joints, connective tissue, and organs including the heart." (PMID 32292401, 2020). "Two genes, TREML4 and IL16, contained meQTL and were also significantly hypomethylated in African American lupus patients." (PMID 33108347, 2020). "Reduced clearance of necrotic material in lupus patients might provide more stimulation to TREML4 and TLRs, promoting the exaggerated type I IFN response seen in lupus patients and contributing to the development of renal disease in lupus." (PMID 33108347, 2020). "Indeed, it has been observed that lupus-prone MRL/lpr mice have higher survival, produce fewer dsDNA autoantibodies, and develop less renal damage when Treml4 is knocked out." (PMID 33108347, 2020).
Sepsis (2 papers, 2020 to 2024). Sepsis is defined as life-threatening organ dysfunction caused by a dysregulated host response to infection. "Increased clearance of P. aeruginosa with reduced myeloperoxidase production in Treml4-/- mice meant that these mice will be better protected against infection and sepsis compared to the WT littermates." (PMID 33336149, 2020). "To understand the function of TREML4 in sepsis, we generated Treml4-/- mice using the CRISPR/Cas9 system." (PMID 33336149, 2020). "Importantly, ablation of neutrophils with anti-Ly6G antibodies reversed the protective phenotype observed in Treml4-/- mice, underscoring the importance of neutrophils in sepsis." (PMID 33336149, 2020). "However, during polymicrobial sepsis, all cytokines tested, including IL-6, were greatly reduced in Treml4-/- mice." (PMID 33336149, 2020). "Indeed, Treml4 deletion afforded almost absolute protection from sepsis." (PMID 33336149, 2020). "However, on chromosome 6, there is group of genes encoding TREM family proteins located and finding the functional equivalent of mouse TREML4 and developing blocking monoclonal antibodies (mAbs) will be the next challenge in developing new therapeutics in treating polymicrobial sepsis." (PMID 33336149, 2020). "It is worth noting that none of the apoptotic genes previously associated with sepsis-mediated lymphopenia such as Bim and Puma was identified in the screen, suggesting that their effect could be additive and Treml4 is possibly the upstream regulator of the process." (PMID 33336149, 2020). "Characterising the Treml4 gene knockout mice revealed new insights into the relative roles of TLR4 and TREML4 in inducing the inflammatory cytokine storm during sepsis." (PMID 33336149, 2020).
Atherosclerotic lesion (1 paper, 2022). A lesion associated with atherosclerosis, a multifactorial and multipart progressive disease manifested by the focal development within the arterial wall of lesions, that ranges from the development of a fatty streak, plaque progression, and plaque disruption. "Genetic polymorphisms that increase TREML4 mRNA expression in human peripheral blood cells are associated with the progression and extent of coronary atherosclerotic lesions." (PMID 36264674, 2022).
lupus nephritis (1 paper, 2022). Glomerulonephritis in the context of systemic lupus erythematosus. "Since patrolling monocytes play a role in glomerular inflammation in murine lupus nephritis, Treml4 expression may enhance the inflammatory response to injured glomerular endothelial cells." (PMID 36264674, 2022). "Treml4−/− MRL/lpr mice have lower autoantibody and interferon-α production and improved survival vs. Treml4+/+ controls, suggesting that Treml4 plays a causal role in lupus nephritis by upregulating TLR7-driven interferon production." (PMID 36264674, 2022).
tumor (2 papers, 2022 to 2023). "We observed that nonclassical Ly6Clo monocytes in the tumor-draining mediastinal lymph nodes were phenotypically distinct from Ly6Clo monocytes in the blood, displaying lower expression of Treml4 and CD16.2." (PMID 37426658, 2023). "The targeting of diverse antigens to Treml4+ cDC1 by anti-Treml4 antibodies elicited both CD4+ and CD8+ T cell responses, but the effects of antigen delivery on disease severity in various models, including tumor transplantation and EAE, remain to be more fully elucidated." (PMID 35225867, 2022).
cancer (1 paper, 2020). A tumor composed of atypical neoplastic, often pleomorphic cells that invade other tissues. "The triggering receptor expressed on myeloid cells 4 (TREML4) is a Ig superfamily member and rarely reported in cancer." (PMID 33323544, 2020).
cardiovascular disease (1 paper, 2020). "Finally, we have found that several inflammatory pathways potentially related to cardiovascular disease are regulated by Treml4 in oxLDL-loaded murine macrophages, suggesting a role for Treml4 in macrophage iron homeostasis and glucose metabolism." (PMID 32292401, 2020). "Together, our results suggest that Treml4 plays a role in the development of cardiovascular disease, as indicated by Treml4-dependent dysregulation of macrophage inflammatory pathways, macrophage metabolism and promotion of vulnerability features in advanced lesions." (PMID 32292401, 2020). "However, the role of TREML4 in the pathogenesis of cardiovascular disease remains incompletely defined." (PMID 32292401, 2020). "Thus, despite well-defined differences in atherogenesis between mouse and humans, our results expand on recent genetic association studies and put forward several lines of evidence warranting future investigation into a definitive role for Treml4 in cardiovascular disease." (PMID 32292401, 2020).
TREML4 also shares sentences with these, for which no sentence is quoted: acute myocardial infarction (1 paper); bacterial sepsis (1); coronary artery (1); Diabetes mellitus type 2 (1); gout (1); heart failure (1); infection (1); kidney failure (1); myocardial infarction (1); myocardial ischemia (1); renal disease (1).